CD24 (CD24 molecule)
Diseases named in the same sentence as CD24 in open-access papers (continued):
Sharing a sentence is not in itself a finding about the gene and the disease.
cancer (continued). "Considering their roles in cancer, the CD24-induced upregulation of miR-199a-3p, 199a-5p, and 34b* was not explained in the context of CSC phenotype acquisition." (PMID 38360723, 2024). "In summary, we identified overexpression of CD24, CTNNB1, and SOX4 signatures in CRC, revealing their association in promoting tumorigenic properties, cancer stemness, and resistance to therapy." (PMID 38203779, 2024). "More significantly, CD24 has been regarded as a cancer biomarker since cancer cells frequently express it, particularly in solid tumors." (PMID 38279998, 2024). "Thirdly, CD24 targeting can be combined with other forms of cancer therapy, including traditional chemotherapy, radiation, or other immunotherapies that target different pathways or mechanisms, potentially leading to synergistic effects." (PMID 38881902, 2024). "Rab27A expression is upregulated in MDA-MB-231 grown as mammospheres compared with those grown as adherent cells, and reducing Rab27A expression decreases mammosphere formation by lowering the proportion of cancer-initiating CD44+/CD24−/low cells." (PMID 38543182, 2024). "In the immune checkpoint module, the double‐high group would activate the immune system more than the single‐high group, resulting in a particular interaction between cancer cells and immune cells mediated by CD24‐SIGLEC10." (PMID 38822457, 2024). "This exploration of CD24 and other immune checkpoints continues to evolve as more is learned about their roles in cancer and the immune system." (PMID 38881902, 2024). "More and more research are now increasingly focusing on the potential of CD24 as a novel target in cancer treatment, spurred by the need to find more effective and safer treatment options in light of the setbacks experienced with CD47-targeted therapies." (PMID 38881902, 2024). "During the metastasis of OC, P-selectin is overexpressed on the surface of mesothelial cells and cancer cells attach to P-selectin through CD24, resulting in increased adhesion between cancer and mesothelial cells." (PMID 39513610, 2024). "CD24 is increasingly recognized for its multifaceted role in cancer pathogenesis, serving as a critical biomarker, prognostic indicator, and therapeutic target." (PMID 38881902, 2024). "In summary, this review focuses on the role of CD24 in the immune system and provides evidence for CD24 as a promising immune checkpoint for cancer immunotherapy." (PMID 38487533, 2024). "Further investigations need to be done to explore the clinical significance of CD24 expression in relation to different cancers." (PMID 38279998, 2024). "Targeting the CD24/Signlec-10 signaling pathway is a promising cancer immunotherapy strategy, according to numerous studies, including preclinical studies and clinical trials." (PMID 38279998, 2024). "Due to CD24's expression in immune and nervous system cells as well as cancer cells, cross-reactivity poses the biggest threat to cancer immunotherapy." (PMID 38279998, 2024). "CD24 is a glycosylphosphatidylinositol-anchored protein that plays a crucial role in various physiological and pathological processes, including cancer progression." (PMID 38881902, 2024). "The authors postulated that the upregulation of CD24 in cancers, such as ovarian cancer and triple-negative breast cancer, facilitates immune escape." (PMID 38254780, 2024). "Here, we performed a systematic pan-cancer analysis of the gene expression levels and clinical correlation of CD24." (PMID 39791710, 2024). "IF results acquired from consecutive sections of BC tissue in patient 2 showed robust CD47 and CD24 protein expression by cancer cells, indicating redundancy of the two membrane-bound “don’t-eat-me” signals." (PMID 38971872, 2024). "The synergy between CD24 monoclonal antibodies and chemotherapy drugs or cytotoxic agents presents a potent strategy for combating aggressive cancers." (PMID 38881902, 2024).
cancer (continued). "In particular, CD24 positiveness is identified as a cancer stem cell marker for various types of cancer, such as gastric cancer, colorectal cancer, cervical cancer, etc.." (PMID 38339250, 2024). "Here the authors report the design of a peptide-antibody combo-supramolecular in situ assembled CD47 and CD24 bi-target inhibitor that enhances the phagocytic ability of macrophages and improves response to anti-PD-1 in preclinical cancer models." (PMID 38971872, 2024). "The linkage allowed for active targeting of CD24 overexpressing cancer cells, thereby exerting a synergistic macrophage immunomodulation." (PMID 38971872, 2024). "In this way, CD24 indirectly facilitates cancer cell metastasis by triggering the EGFR, ERK1/2, and Akt signaling pathways." (PMID 38881902, 2024). "Given the permissive predisposition of ZIKV to CD24-expressing targets, this approach also offers the opportunity to address progenitor cells involved in a broad array of cancers, not only in the pediatric field but among adult CD24-expressing cancers as well." (PMID 38214542, 2024). "There are ongoing preclinical studies and clinical trials evaluating the effectiveness of monoclonal antibodies that target CD24 in cancer therapy." (PMID 38881902, 2024). "Starvation therapies utilizing GOx face challenges due to the absence of precise targeting and the inhibitory effects of the CD24/Siglec-10 signaling pathway, which can protect cancer cells from being engulfed by macrophages." (PMID 39479443, 2024). "In this study, we performed a systematic pan-cancer analysis of the CD24 gene expression and clinical correlation." (PMID 39791710, 2024). "The small, heavily glycosylated protein CD24 is primarily expressed by many immune cells and is highly expressed mostly in cancer cells." (PMID 38279998, 2024). "CD24 is predominantly expressed on the surface of the T and B lymphocytes and is overexpressed in multiple cancer cell types." (PMID 39872538, 2024). "H&E staining of xenograft sections in both the IgG control and anti-CD24 groups revealed that the cancer cells were densely arranged in bands and clusters, with disordered arrangement." (PMID 38971872, 2024). "The binding of CD24 to these receptors can influence immune cell signaling pathways, potentially leading to immunosuppressive effects that can be exploited by cancer cells to evade immune detection and destruction." (PMID 38881902, 2024). "This proliferation coincided with the acquisition of cancer stem cell features, including reduced cell size, enhanced self-renewal capacity, and elevated levels of the cancer stem cell surface marker CD24 and pluripotent transcription factor SOX2." (PMID 38942903, 2024). "More recently, CD24 has garnered attention in oncology, particularly for its role in identifying cancer stem cells (CSCs)." (PMID 39184916, 2024). "Analogous to CD47–SIRPα interaction, CD24 on cancer cells inhibits phagocytosis by binding to macrophage Siglec-10." (PMID 38831013, 2024). "CD24 expression level has a significant positive correlation with cancer staging and nodal metastasis status." (PMID 38914670, 2024). "Interaction between CD24 and Siglec-10 effectively transmits a “don’t eat me” signal, inhibiting the phagocytic activity of these immune cells against cancer cells." (PMID 38881902, 2024). "The BLI intensity started to increase soon after injection of cancer cells in the IgG control and anti-CD24 groups, and patchy metastatic lesions formed in the liver region." (PMID 38971872, 2024). "High expression of CD44/CD24 cells are recognized as a subpopulation with higher clonogenic and tumor initiation potential leading to aggressive cancer types and poor prognosis." (PMID 38787133, 2024). "CD24 is known to be a “don’t eat me” signal and plays an important role in regulating the phagocytosis of cancer cells by macrophages." (PMID 38168654, 2024).
cancer (continued). "We investigated the effect of polystyrene nanoparticles (PSNPs) on cancer cell stemness using flow cytometric analysis of CD24, CD44, ABCG2, ALDH1 and their combinations." (PMID 38787133, 2024). "CD24 plays a crucial role in cancer resistance through mechanisms that enhance cancer cell survival, enable immune evasion, and promote therapy resistance." (PMID 38881902, 2024). "Another approach involves the use of dendritic cells loaded with cancer cells coated with antibodies that target a variety of surface antigens, such as CD24." (PMID 38881902, 2024). "CD24 is a novel “don’t eat me” signal and is used by cancer cells to protect themselves from phagocytosis by macrophages." (PMID 38168654, 2024). "CD24 and MET expression are associated with cancer malignancy and cancer stem‐like cell (CSC) features in various cancers." (PMID 38030594, 2024). "CD24 is involved in the regulation of several signaling pathways that are important for cancer progression." (PMID 38881902, 2024). "Herein we will review the latest studies involving anti-CD24 antibody treatments in cancer patients, comprising seven distinct investigations." (PMID 38881902, 2024). "Recent studies elucidate the molecular pathways underpinning the CD24-Siglec-10 axis, highlighting its significance in immune tolerance and exploitation by cancer cells to evade immune surveillance." (PMID 38881902, 2024). "We first explored an established cancer stemness marker, CD24 and an EMT marker for SOX4 expression." (PMID 38203779, 2024). "These clinical efforts underscore the ongoing investigations into CD24 as a therapeutic target in various cancers, highlighting the complexities and challenges encountered in translating preclinical findings to clinical therapies." (PMID 38881902, 2024). "This study discusses the characteristics and workings of CD24/Siglec-10-targeted immunotherapy and offers a summary of current advances in CD24/Siglec-10-related immunotherapy research for cancer." (PMID 38279998, 2024). "As expected, CD24 blockade increased the phagocytosis of cancer cells by macrophages in vitro, as shown in the flow cytometry results." (PMID 38168654, 2024). "Treatment with most of the extracts induced a significant decrease in the relative expression of the cancer stem cell (CSC)-related genes CD24, CD133, NANOG and OCT-4." (PMID 39683626, 2024). "We found that the amount of the EpCAM-positive EVs (also CD81-positive) or the CD24-positive EVs increased as the cancer progressed from Stage II to III." (PMID 39513819, 2024). "The strategy combing CD24 inhibitors with immune checkpoint inhibitors offers a promising approach for treating aggressive cancers." (PMID 38881902, 2024). "Of note, cluster C6 cancer cells mainly came from two patients (P8 and P9), in which more than 90% of cancer cells were demarcated with triple expression of CD24/CD47/ICAM1." (PMID 38169544, 2024). "Strong cancer immunotherapy effects can be achieved by simultaneously inhibiting CD24 and activating CRT in macrophages." (PMID 38279998, 2024). "Cancer stem cells are identified using cell surface markers and although no markers are exclusively specific to LCSCs15, we identified CD24, CD44, CD133, and EpCAM that are correlated to CAR expression." (PMID 39730609, 2024). "For example, CD24 was also implied to be a downstream target of Ral GTPase signaling, involving in cancer cell motility." (PMID 37919766, 2023). "To date, many studies have shown that CD24 is abundantly expressed in various human cancers and is correlated with a poor prognosis." (PMID 37894750, 2023). "Further studies will be accordingly essential to demonstrate the various functions of CD24 in cancer pathogenesis and potential molecular mechanisms involved." (PMID 37919766, 2023). "To date, there have been two completed clinical trials focused on testing CD24-blocking drugs in cancer patients." (PMID 38313430, 2023).
cancer (continued). "Although its expression on immune cells leads to harmful adverse effects, investigators have also attempted to explore the efficacy of anti-CD24-based cancer therapy in preclinical models." (PMID 36882399, 2023). "Treatment with an anti-CD24 antibody was found to promote the phagocytic clearance of cancer cells by macrophages by blocking CD24–Siglec-10 interaction." (PMID 37894750, 2023). "Upon internalization by cancer cells, the dAbPD−L1/CD24-mPDA@CuO2 NRs underwent decomposition within the acidic endo/lysosomal compartments, releasing Fenton catalytic Cu2+ ions and H2O2." (PMID 37875918, 2023). "HIF acts as a transcription factor to induce CD24 expression at the transcriptional level, and promote the cancer invasion." (PMID 37359556, 2023). "Nevertheless, there are some conflicting reports on the role of CD24 in cancer (Ni, Zhao & Wang, 2020)." (PMID 37842046, 2023). "This review builds on existing research on CD24, exploring its structure and role in cancer, with a focus on current studies of antibody drugs targeting the protein and potential treatments." (PMID 38137380, 2023). "Phagocytosis increased when M2‐like macrophages were co‐cultured with cancer cells, particularly in the case of paired DEMs blockade (i.e. anti‐CD24 + anti‐CD47) combined with Rituximab." (PMID 37654003, 2023). "Here, we reviewed and summarized recent advances in anti-CD24 antibodies therapy were evaluated in seven studies on cancer patients." (PMID 37919766, 2023). "Researchers have extensively investigated the use of antibodies that target CD24 for cancer treatment." (PMID 38313430, 2023). "Ablation of either CD24 or Siglec‐10, as well as blockade of the CD24 / Siglec‐10 interaction, is a promising strategy for cancer immunotherapy." (PMID 36794651, 2023). "Especially, CD24 has been shown to influence the phosphorylation and activity of key components in B cells and cancer cells." (PMID 37919766, 2023). "CD24 is a promising target for cancer immunotherapy, which has recently been recognized as one of the most effective approaches in the treatment of many tumors." (PMID 37846296, 2023). "CD24 is becoming a compelling therapy target for the immunotherapy of cancer due to its important role in both the regulation of the immune response as well as the tumorigenesis process." (PMID 37359556, 2023). "In preclinical investigations, monoclonal antibody inhibition of the CD24-Siglec-10 interaction for cancer immunotherapy has gained increasing interest and demonstrated encouraging outcomes." (PMID 37846296, 2023). "Nevertheless, this research section also demonstrates noteworthy differences in CD24 expression among various cancer cell lines." (PMID 38137380, 2023). "This confirmed that the targeted degradation of CD24 by Nanosphere‐AntiCD24 affected communication between macrophages and cancer cells through the CD24/Siglec‐10 signaling pathway." (PMID 36866919, 2023). "The results of the profiling of the plasma samples showed exosomes from cancer patients had higher levels of EpCAM and CD24 expression in comparison to non‐cancer patients." (PMID 35898167, 2023). "In contrast to these potential beneficial effects, CD24 is overexpressed in ovarian cancer and breast cancer, and acts as a “don’t eat me” signal to protect cancer cells from phagocytosis that in turn promotes immune evasion." (PMID 37346042, 2023). "CD24, a severely sialylated protein, is highly expressed in various cancer cells and is recognized by Siglec-10 on immune cells such as macrophages." (PMID 37894750, 2023). "M2-shifted TAMs also support CAMs activity by macrophage inflammatory protein-1β that activates P-selectin secretion by CAMs, followed by stimulation of CD24 on the cancer cells’ surface and increased adhesion." (PMID 37448521, 2023). "Though significant progress has been achieved in understanding the functions of CD24 in cancer, research on its role in neural cancers has been relatively limited." (PMID 38313430, 2023).
cancer (continued). "Cluster of differentiation 24 (CD24), a mucin-like highly glycosylated molecule has been extensively studied as a cancer stem cell marker in a variety of solid cancers." (PMID 37919766, 2023). "In comparison with other innate immune checkpoints, CD24 expression is extensively upregulated in diverse cancer cells." (PMID 38137380, 2023). "The ‘magic’ of CD24, once solely attributed to cancer, now inspires a new paradigm in understanding its multifunctionality in human health and disease, offering exciting prospects for medical advancements." (PMID 38313430, 2023). "As a marker of cancer stem cells, CD24 is widely expressed in various cancer stem cells and various cells of the nervous system." (PMID 37057399, 2023). "We found cancer stem cell gene, CD24 (logFC = 0.9), and therapy resistant genes, CD46 (logFC = 0.3) and CD55 (logFC = 0.4) expressed in ES1, ES2, and ES3 combined, compared to ES0, and cancer stem cell marker, CD59 to be the highest in ES1 (logFC = 0.4)." (PMID 38328306, 2023). "On the other hand, E2F3 and CD24, which are also commonly dysregulated in cancer were classified as NAP genes in our analysis as they were up-regulated in at least 30% of the patients but were not identified by the all-patients analysis." (PMID 36737737, 2023). "As such, the combination of anti-CD24 antibodies and chemotherapeutic drugs is more effective for cancer stem cells that are resistant to chemotherapy." (PMID 37484024, 2023). "CD44 and CD24 are the “original” markers used to characterize cancer stem cells (CSCs) in breast cancer." (PMID 37709737, 2023). "After treatment, cancer cells succumbed to starvation treatment, and the effect of immunotherapy was enhanced by relieving the immunosuppression induced by the CD24/Siglec‐10 pathway." (PMID 36866919, 2023). "Interrupting CD24-Siglec-10 interaction by anti-CD24 antibody improves phagocytic clearance of cancer cells by macrophages." (PMID 38008741, 2023). "The results revealed that the cancer cell subclusters c8_TOP2A, c9_HMGB2, c12_MKI67, and c13_TK1 were dominantly in a cycling state, while c1_TCN1, c2_CD74, c3_CD24, c5_CEACAM6, and c10_SAT1 were mainly in a quiescent state." (PMID 36529697, 2023). "CD24, a powerful anti-phagocytic “don’t eat me” signal, can shield cancer cells from attack by macrophages that are Siglec-10-expressing." (PMID 37846296, 2023). "In human cancer cells, the interaction between CD24 and P-selectin facilitates the rolling of specific cancer cells on endothelial cells." (PMID 38137380, 2023). "CD24 attracts the increasing interests for the expression in human cancer cells to mediate the cell invasion and immune evasion." (PMID 37359556, 2023). "Given the close correlation between CSCs and CD24, CD24 emerges as a promising target for the treatment of cancer initiation and recurrence." (PMID 38137380, 2023). "In this review, we provide an overview of the progress made in the use of antibodies targeting CD24 as an anti-cancer therapy." (PMID 38137380, 2023). "CD24 is highly expressed not only in various cancer cells but also in individual normal tissues such as the oesophagus and thyroid." (PMID 38137380, 2023). "Since current knowledge on the epigenetic mechanism of CD24 is very limited, it became necessary to further investigate the molecular cell biology, the clinical setting as well as genetics of CD24 in relation to cancer." (PMID 37919766, 2023). "CD24 has emerged as a promising therapeutic target in cancer due to its significant role in the disease." (PMID 38313430, 2023). "CD24 and its ligands cannot be disregarded as participants in the formation of key features of cancer." (PMID 37484024, 2023). "In various cancers, tumor-derived ligands (e.g., CD24 and sialoglycans) induce monocyte differentiation toward protumor TAM phenotype by Siglec-7, Siglec-9, Siglec-10, Siglec-15, and Siglec-E." (PMID 38008741, 2023).